PAN3-AS1 (PAN3 antisense RNA 1)
Gene: Long non-coding RNA gene on chromosome 13 (28,136,561 to 28,138,497, reverse strand). Ensembl gene ENSG00000261485.
Diseases named in the same sentence as PAN3-AS1 in open-access papers:
PAN3-AS1 is named in the same sentence as 1 disease in open-access papers, as found by Europe PMC text mining. Sharing a sentence is not in itself a finding about the gene and the disease. The quoted sentences say what the papers report.
tumor (1 paper, 2025). "Interestingly, we found that PAN3-AS1 abundance is inversely linked to TMB and MSI in many tumor categories, which also means that these patients respond poorly to immunotherapy." (PMID 41502505, 2025).